ADAMTS12 (ADAM metallopeptidase with thrombospondin type 1 motif 12)
Diseases named in the same sentence as ADAMTS12 in open-access papers (continued):
Sharing a sentence is not in itself a finding about the gene and the disease.
cervical cancer (2 papers, 2023 to 2025). A primary or metastatic malignant neoplasm involving the cervix. "We concluded that ADAMTS12 level was an independent risk factor for survival and prognosis of cervical cancer patients (HR = 2.339, P = 0.043)." (PMID 37642715, 2023). "We also explored the function of ADAMTS12 in cervical cancer cells and its underlying mechanisms." (PMID 37642715, 2023). "In this research, we explored the relationship between the expression level of ADAMTS12 in cervical cancer tissues and clinicopathological characteristics, and verified that ADAMTS12 is an independent risk factor influencing the prognosis of cervical cancer patients." (PMID 37642715, 2023). "After transfection with ADAMTS12 plasmid, the migration and invasion of cervical cancer cells were significantly enhanced, but the cloning and proliferation ability were not affected." (PMID 37642715, 2023). "We studied the expression level of ADAMTS12 in cervical cancer tissue and its relationship with clinicopathological features." (PMID 37642715, 2023). "In conclusion, this study shows that ADAMTS12 gene is closely related to migration and invasion ability of cervical cancer, and can be used as an indicator of poor prognosis of patients." (PMID 37642715, 2023). "To seek the regulatory pathway of ADAMTS12 in cervical cancer, we used the transcriptome data of 306 cases of cervical cancer in the TCGA database and conducted a single-gene correlation analysis of the ADAMTS12 gene by R software." (PMID 37642715, 2023). "We found a relationship between ADAMTS12 expression levels and the clinicopathological features of cervical cancer, which confirmed our previous inference, and we conducted further studies on its predictive ability." (PMID 37642715, 2023). "The malignant phenotype of ADAMTS12 in cervical cancer cell lines was verified by functional experiments." (PMID 37642715, 2023). "Further, upregulation of ADAMTS12 gene can affect mTOR signaling pathway, suggesting that the ADAMTS12 gene can provide a new target for diagnosis and treatment of cervical cancer." (PMID 37642715, 2023). "RT-qPCR was used to detect ADAMTS12 in cervical cancer cell lines (HeLa, CaSki, and SiHa) at RNA levels." (PMID 37642715, 2023). "Our study found that ADAMTS12 overexpression in cervical cancer cells upregulated the phosphorylation levels of mTOR and 4E-BP1." (PMID 37642715, 2023). "The molecular expression level and phosphorylation levels of PI3K, mTOR, and 4EBP1D proteins in cervical cancer cells with the ADAMTS12 overexpression group were detected by WB." (PMID 37642715, 2023). "In conclusion, TCGA data analysis suggested that the higher the ADAMTS12 level, the worse the prognosis of cervical cancer patients." (PMID 37642715, 2023). "The immunofluorescence assay showed that the cytoplasm of cervical cancer cells is the main expression site of ADAMTS12." (PMID 37642715, 2023). "Most of the patients with highly differentiated cervical carcinoma expressed low level of ADAMTS12, while most of the patients with poorly differentiated cervical carcinoma expressed a high level of ADAMTS12." (PMID 37642715, 2023). "Co-Immunoprecipitation combined with mass spectrometry showed that ADAMTS12 may affect the biological function of cervical cancer through TGF-β signaling pathway, which is a considerable mechanism affecting tumor immune microenvironment." (PMID 37642715, 2023). "The expression level of ADAMTS12 in cervical cancer cell lines was detected at the protein level." (PMID 37642715, 2023). "Therefore, we believe that ADAMTS12 can promote the migration and invasion ability of cervical cancer cells." (PMID 37642715, 2023). "This article provides a preliminary basis for studying the mechanism of ADAMTS12 in cervical cancer, and it also suggests a new direction for gene therapy of cervical cancer, and proposes a theoretical basis for ADAMTS12 gene as a therapeutic target for cervical cancer." (PMID 37642715, 2023).
cervical cancer (continued). "It is speculated that ADAMTS12 may regulate the invasion and migration of cervical cancer cells by affecting the mTOR signaling pathway." (PMID 37642715, 2023). "We have reason to speculate that ADAMTS12 may play a significant role in cervical cancer, so it is necessary to study the role of this gene in cervical cancer." (PMID 37642715, 2023). "Cervical cancer is a common malignant gynecological tumor, but it is unclear whether ADAMTS12 is related to cervical carcinogenesis." (PMID 37642715, 2023). "First, we analyzed ADAMTS12 levels in 382 cervical cancer patients and found that ADAMTS12 levels were higher in tumors with a higher degree of malignancy, including patients with high FIGO stage, poorly differentiated status, and pathological type of non-squamous cell carcinoma." (PMID 37642715, 2023). "The results suggest that ADAMTS12 can be successfully overexpressed in vitro cervical cancer cells, and ADAMTS12 may be modified in vitro, resulting in protein molecular weight increase." (PMID 37642715, 2023). "Therefore, we speculate that ADAMTS12 may affect TGF-β1 expression to participate in the progression of cervical cancer." (PMID 37642715, 2023). "In addition, ADAMTS12 regulated the malignant function of cervical cancer, which may also be related to B cells and macrophages." (PMID 37642715, 2023). "Therefore, we further explored the relationship between ADAMTS12 and cervical cancer phenotype." (PMID 37642715, 2023). "In order to research the effects of ADAMTS12 on proliferation of cervical cancer cells, we performed EdU cell proliferation assay, clonogenesis and CCK8 to detect the proliferation indexes of HeLa and CaSki cell transfected with ADAMTS12 plasmid." (PMID 37642715, 2023). "ADAMTS12, an ADAMTS protease family member, has been observed before to exert an impact on the progression of various malignancies, including gastric, pancreatic, and cervical cancers and head and neck squamous cell carcinoma." (PMID 39761856, 2025). "ADAMTS12 level was low in most patients with early cervical cancer (CIS + I), but high in most patients with stage II–IV, suggesting that the ADAMTS12 level increases with the progression of cervical cancer." (PMID 37642715, 2023). "Therefore, we concluded that ADAMTS12 may affect the mTOR signaling pathway through the interacting with TGF-β1, and then affect the biological function of cervical cancer cells." (PMID 37642715, 2023). "Therefore, we speculated that ADAMTS12 activates the PI3K signaling pathway by interacting with proteins in the TGF-β signaling pathway, and then plays a carcinogenic role in cervical cancer." (PMID 37642715, 2023).
colitis (2 papers, 2021 to 2024). Inflammation of the colon. "ADAMTS12 seems to be involved in the resolution of normal inflammatory processes so the absence of this protease increases the symptoms in diseases such as colitis and pancreatitis, as well as damages caused by septicemia in animals deficient in ADAMTS12." (PMID 38396702, 2024). "In this sense, ADAMTS-12 performs essential roles in modulation and recovery from inflammatory processes such as colitis, endotoxic sepsis and pancreatitis." (PMID 33996918, 2021).
esophageal squamous cell carcinoma (2 papers, 2020 to 2021). Esophageal squamous cell carcinoma (ESCC) is a type of esophageal carcinoma (EC) that can affect any part of the esophagus, but is usually located in the upper or middle third. "One research had pointed out that ADAMTS12 was abnormally overexpressed in esophageal squamous cell carcinoma and negatively regulated by the expression of migration inhibitor lncRNA HCG2245." (PMID 34040054, 2021).
intervertebral disc degeneration (2 papers, 2014 to 2020). "It was reported that the expressions of ADAMTS-7 and ADAMTS-12 in the endplate cells isolated from patients with degenerative disc disease were significantly increased." (PMID 24876675, 2014). "In a static pressure-induced rat model with caudal intervertebral disc degeneration, the mRNA levels of ADAMTS4, ADAMTS5, ADAMTS7, and ADAMTS12 were found to be increased significantly." (PMID 32855969, 2020). "Moreover, in intervertebral disc degenerative (IVD) rat model, the level of ADAMTS-7 was significantly increased in the early phase while the level of ADAMTS-12 was increased in the latter phase." (PMID 24876675, 2014).
liver fibrosis (2 papers, 2025 to 2026). "Non-hepatocyte cell-type QTL analyses exposed previously obscured mechanisms, such as an eQTL for ADAMTS12 in liver sinusoidal endothelial cells potentially involved in liver fibrosis, demonstrating that single-nucleus approaches can capture regulatory events missed in bulk analyses." (PMID 41338218, 2025).
myocardial infarction (2 papers, 2024). Gross necrosis of the myocardium, as a result of interruption of the blood supply to the area, as in coronary thrombosis. "In a myocardial infarction mouse model, Adamts12–/– mice exhibited reduced heart fibrosis and preserved left ventricular ejection fraction (LVEF)." (PMID 39286974, 2024). "Predictive analysis of fibroblast cell states in the spatial data showed that knockout of Adamts12 abrogated the expansion of epicardial and Atf3+ injury-responsive fibroblasts.ADAMTS12 expression was also observed in the ischemic zone of myocardial infarction in a human dataset." (PMID 39286974, 2024). "To assess whether the profibrotic effect of Adamts12 is conserved across organs, we next performed myocardial infarction (MI) surgery or sham surgery in WT and Adamts12–/– mice." (PMID 39286973, 2024).
pancreatic cancer (2 papers, 2019 to 2024). "In pancreatic cancer, ADAMTS12 facilitated cell migration and epithelial-mesenchymal transition and indicates poor prognosis." (PMID 38167385, 2024).
preeclampsia (2 papers, 2016 to 2025). Preeclampsia is a hypertensive disorder of pregnancy that is characterized by new-onset hypertension with proteinuria presenting after 20 weeks of gestation, and depending on mild or severe forms may initially present with severe headache, visual disturbances, and hyperreflexia. "Deficiency of ADAMTS-12 may cause defective trophoblast differentiation, abnormal remodeling of spiral arteries, and abnormal development of the placenta, which induces preeclampsia." (PMID 28913111, 2016).
squamous cell carcinoma (2 papers, 2023 to 2024). A carcinoma arising from squamous epithelial cells. "However, in contrast to the expression of the ADAMTS9 gene, the expression of the ADAMTS12 gene was overexpressed in tumor tissue, both in adenocarcinoma (p < 0.0001) and squamous cell carcinoma (p < 0.0001)." (PMID 38339175, 2024). "However, similar to ADAMTS9, the ADAMTS12 gene expression did not appear to have any significant effect on survival duration in squamous cell carcinoma (p = 0.3183)." (PMID 38339175, 2024).
adenoma (1 paper, 2020). A neoplasm arising from the epithelium. "Immunohistochemistry staining of tumor sections from these mice revealed some level of expression of ADAMTS12 in the region surrounding the adenoma, but not in the highly-proliferative Ki-67+ cells." (PMID 32732999, 2020).
autoimmune disease (1 paper, 2024). A disorder resulting from loss of function or tissue destruction of an organ or multiple organs, arising from humoral or cellular immune responses of the individual to their own tissue constituents. "As such, it is possible that loss of Adamts12 with subsequent loss of CD200/CD200R fibroblast-macrophage signaling leads to a dysfunctional attenuation of inflammation in response to other stimuli, i.e., in infection and autoimmune disease, but not fibrosis." (PMID 39286973, 2024).
cervical squamous cell carcinoma (1 paper, 2023). A squamous cell carcinoma arising from the cervical epithelium. "Our data showed that a significant association was found between ADAMTS12 level and pathological type (P = 0.012), most patients with cervical squamous cell carcinoma (SCC) expressed low ADAMTS12, while in non-cervical squamous cell carcinoma that was high." (PMID 37642715, 2023).
choriocarcinoma (1 paper, 2024). An aggressive malignant tumor arising from trophoblastic cells. "I human choriocarcinoma, ADAMTS12 promotes cell-extracellular matrix adhesion and invasion by a αvβ3 integrin heterodimer related mechanism." (PMID 38167385, 2024).
germ cell tumor (1 paper, 2018). A benign or malignant, gonadal or extragonadal neoplasm that originates from germ cells. "ADAMTS12 and MGMT were hypermethylated in almost all of the endometrioid, mucinous, and germ cell tumors." (PMID 29882921, 2018).
head and neck cancer (1 paper, 2023). A primary or metastatic malignant neoplasm affecting the head and neck. "Importantly, ADAMTS12 was shown to promote cell invasion and the migration of head and neck cancer cells via the activation of the PI3-AKT pathway." (PMID 37835389, 2023).
heart failure (1 paper, 2024). Inability of the heart to pump blood at an adequate rate to meet tissue metabolic requirements. "To this end, we scored fibroblasts from the previously used scRNA reference dataset of fibroblasts in murine heart failure based on their expression of genes upregulated in active ADAMTS12–expressing cells (in comparison with ADAMTS12-KO or inactive ADAMTS12–expressing cells)." (PMID 39286973, 2024).
lung adenoma (1 paper, 2020). A benign, well circumscribed epithelial neoplasm that arises from the bronchus or the lung parenchyma. "Additionally, we have shown that mice treated with urethane have a several fold increase in the susceptibility to develop lung adenomas when ADAMTS12 is knocked out." (PMID 32732999, 2020).
lung squamous-cell carcinoma (1 paper, 2025). "The findings indicate significantly higher ADAMTS6, ADAMTS9, and ADAMTS12 promoter methylation in the tissue affected by cancer compared with normal tissue in patients with squamous-cell lung cancer (p < 0.001)." (PMID 39940703, 2025).
lymph node metastasis (1 paper, 2023). "Multivariate cox regression analysis indicated that ADAMTS12 level, high FIGO stage and positive lymph node metastasis were independent risk factors." (PMID 37642715, 2023). "We used Cox hazard proportional regression model for analysis, ADAMTS12 level, FIGO stage, tumor differentiation type, lymph node metastasis, adjuvant chemoradiotherapy treatment, and pathological type were all used as potential covariates to participate in univariate Cox regression analysis." (PMID 37642715, 2023).
melanoma (1 paper, 2020). A malignant, usually aggressive tumor composed of atypical, neoplastic melanocytes. "Indeed, it resulted quite appealing the fact that such positive association did occur with high expression of other ADAMTS proteases (ADAMTS2, ADAMTS4, ADAMTS5, ADAMTS9, ADAMTS12 and ADAMTS14) that definitively implied a key role of these proteases during melanoma progression." (PMID 32230715, 2020).
metastatic tumors (1 paper, 2020). "ADAMTS12 is associated with ovarian and renal cancer metastases, and its expression level is significantly elevated in metastatic tumors compared to primary tumors." (PMID 32884571, 2020).
Myocardial fibrosis (1 paper, 2024). "Especially in the context of myocardial fibrosis, in which ADAMTS12 loss not only reduced fibrosis but also preserved LVEF, ADAMTS12 inhibition could be an interesting therapeutic approach." (PMID 39286974, 2024).
non-small cell lung carcinoma (1 paper, 2025). A group of at least three distinct histological types of lung cancer, including non-small cell squamous cell carcinoma, adenocarcinoma, and large cell carcinoma. "This study aimed to evaluate the methylation levels of the ADAMTS6, ADAMTS9, and ADAMTS12 genes in non-small-cell lung cancer (NSCLC) using data from bioinformatics databases." (PMID 39940703, 2025).
Obesity (1 paper, 2026). Accumulation of substantial excess body fat. "Compared to the normal pregnancy group, the levels of DCN and ADAMTS12 showed an increasing trend in the gestational obesity group and the GDM group." (PMID 41876836, 2026). "Notably, DCN and ADAMTS12 were markedly higher in the GDM with obesity group compared to either the gestational obesity or GDM-alone groups." (PMID 41876836, 2026).
ovarian carcinoma (1 paper, 2023). A malignant neoplasm originating from the surface ovarian epithelium. "In ovarian cancer, ADAMTS12 was overexpressed in intestinal metastatic tissues, suggesting that the high expression of ADAMTS12 gene predicts the occurrence of intestinal metastasis and invasive cancer." (PMID 37642715, 2023).
prostate adenocarcinoma (1 paper, 2025). "ADAMTS12 expression was found to be lower than in the corresponding normal tissues in prostate adenocarcinoma (PRAD), BRCA, KICH, KIRP, SKCM, and UCAC." (PMID 39940703, 2025).
renal cell carcinoma (1 paper, 2022). "In renal cell carcinoma, ADAMTS12 is listed as one of the seven extracellular matrix (ECM) genes, and the up-regulation and high expression of ADAMTS12 may contribute to metastasis." (PMID 37092087, 2022).
serous carcinomas (1 paper, 2018). "On the other hand, in serous carcinomas, only 51% and 31% of the tumors were found hypermethylated for ADAMTS12 and MGMT, respectively." (PMID 29882921, 2018).